NKAP (NFKB activating protein)
Diseases named in the same sentence as NKAP in open-access papers (continued):
Sharing a sentence is not in itself a finding about the gene and the disease.
cancer (7 papers, 2016 to 2024). A tumor composed of atypical neoplastic, often pleomorphic cells that invade other tissues. "Mutations or dysregulated expression of NF-kappaB-activating protein (NKAP) family genes have been found in human cancers." (PMID 38059855, 2024). "Nuclear factor-κB activating protein (NKAP) is a conserved nuclear protein that acts as an oncogene in various cancers and is associated with a poor prognosis." (PMID 33553160, 2020). "The data was obviously showed that YTHDF1, IGF2BP3 and NKAP were highly expressed in most cancer types." (PMID 35963644, 2022). "To further understand the roles of YTHDF1, IGF2BP3 and NKAP in other cancers, we collected their expression levels from pan-cancer analysis." (PMID 35963644, 2022). "Inhibition of MARCKS phosphorylation is capable of trapping NKAP and inactivating NF-kB signaling, leading to suppression of proinflammatory cytokines as well as attenuation of cancer cell aggressiveness and stemness." (PMID 33754052, 2021). "We analyzed the copy number alterations at the NKAP locus (Xq24) in several human cancers by exploring publicly available datasets of The Cancer Genome Atlas (TCGA)." (PMID 27694884, 2016). "Second, reduced levels of NKAP expression are found in several types of cancers." (PMID 38059855, 2024). "On the other hand, NKAP knockdown also reduces the proliferation of cancers." (PMID 35005769, 2022). "FADD downregulation in certain cancer types—such as T-LBL—might result in the reduced stability of NKAP complexes in the nucleus, contributing to NOTCH hyperactivation frequently found in T-cell lymphoblastic neoplasms." (PMID 31569512, 2019). "The NF-κB activating protein (NKAP), a protein identified in our analysis to interact with unphosphorylated MARCKS, drew our attention owing to its role in directly activating NF-κB signaling, a smoke-related signaling pathway associated with cancer malignancy 10, 23, 24 (right)." (PMID 33754052, 2021). "More importantly, YTHDF1, IGF2BP3 and NKAP were also highly expressed in pan-cancer, which provided the promise of YTHDF1, IGF2BP3 and NKAP as potential therapeutic targets." (PMID 35963644, 2022). "Therefore we next asked whether NKAP was dysregulated in human cancers." (PMID 27694884, 2016). "Emerging evidence suggests a link between altered NKAP/NKAPL activity and cancer development." (PMID 38059855, 2024).
inflammation (1 paper, 2020). Aberrant reaction of the microcirculation characterized by movement of fluid and leukocytes from the blood into extravascular tissues. "In summary, our data revealed that knockdown of MIAT protected against LPS-induced pulmonary inflammation and injury, which was mediated by miR-147a/NKAP axis." (PMID 33318298, 2020). "Together, silencing of MIAT alleviates LPS-induced pulmonary inflammation and injury via regulating miR-147a/NKAP axis." (PMID 33318298, 2020).
NKAP also shares sentences with these, for which no sentence is quoted: hepatocellular carcinoma (3 papers); developmental delay (2); pneumonia (2); acute myocardial infarction (1); craniofacial microsomia (1); diabetes (1); epilepsy (1); genetic disorder (1); hearing loss (1); pancreatic cancer (1); retinitis pigmentosa (1); ventricular septal defect (1).